PSMB3 (proteasome 20S subunit beta 3)
Description:
Non-catalytic component of the 20S core proteasome complex involved in the proteolytic degradation of most intracellular proteins. This complex plays numerous essential roles within the cell by associating with different regulatory particles. Associated with two 19S regulatory particles, forms the 26S proteasome and thus participates in the ATP-dependent degradation of ubiquitinated proteins. The 26S proteasome plays a key role in the maintenance of protein homeostasis by removing misfolded or damaged proteins that could impair cellular functions, and by removing proteins whose functions are no longer required. Associated with the PA200 or PA28, the 20S proteasome mediates ubiquitin-independent protein degradation. This type of proteolysis is required in several pathways including spermatogenesis (20S-PA200 complex) or generation of a subset of MHC class I-presented antigenic peptides (20S-PA28 complex).
Synonyms: HC10-II; MGC4147
Tractability: Small molecule: an approved drug acts on it; a structure with a bound ligand is known; a high-quality ligand is known; it belongs to a druggable protein family. PROTAC: ubiquitination databases record sites on it; its protein half-life has been measured; a small molecule that binds it is known.
Target class: Threonine protease; Protease; Threonine protease T1A subfamily; Threonine protease PBT clan; Enzyme
Gene: Protein-coding gene on chromosome 17 (38,752,736 to 38,764,231, forward strand). Ensembl gene ENSG00000277791.
Subcellular location: Cytoplasm; Nucleus
Pathways (Reactome):
Immune System: AMPK-induced ERAD and lysosome mediated degradation of PD-L1(CD274); Activation of NF-kappaB in B cells; Antigen processing: Ub, ATP-independent proteasomal degradation; Antigen processing: Ubiquitination & Proteasome degradation; CLEC7A (Dectin-1) signaling; Cross-presentation of soluble exogenous antigens (endosomes); Dectin-1 mediated noncanonical NF-kB signaling; Downstream TCR signaling; ER-Phagosome pathway; FCERI mediated NF-kB activation; GSK3B-mediated proteasomal degradation of PD-L1(CD274); Interleukin-1 signaling; NIK-->noncanonical NF-kB signaling; SPOP-mediated proteasomal degradation of PD-L1(CD274); TNFR2 non-canonical NF-kB pathway
Cell Cycle: APC/C:Cdc20 mediated degradation of Securin; APC/C:Cdh1 mediated degradation of Cdc20 and other APC/C:Cdh1 targeted proteins in late mitosis/early G1; Autodegradation of Cdh1 by Cdh1:APC/C; Autodegradation of the E3 ubiquitin ligase COP1; Cdc20:Phospho-APC/C mediated degradation of Cyclin A; FBXL7 down-regulates AURKA during mitotic entry and in early mitosis; G2/M Checkpoints; SCF(Skp2)-mediated degradation of p27/p21; SCF-beta-TrCP mediated degradation of Emi1; Separation of Sister Chromatids; The role of GTSE1 in G2/M progression after G2 checkpoint; Ubiquitin-Mediated Degradation of Phosphorylated Cdc25A; Ubiquitin-dependent degradation of Cyclin D
Signal Transduction: Asymmetric localization of PCP proteins; Degradation of AXIN; Degradation of DVL; Degradation of GLI1 by the proteasome; Degradation of GLI2 by the proteasome; Degradation of beta-catenin by the destruction complex; GLI3 is processed to GLI3R by the proteasome; Hedgehog 'on' state; Hedgehog ligand biogenesis; MAPK6/MAPK4 signaling; Negative regulation of NOTCH4 signaling; Regulation of PTEN stability and activity
and 28 more pathways
Gene Ontology:
Molecular function: protein binding; structural constituent of proteasome
Biological process: proteasomal protein catabolic process; proteasome-mediated ubiquitin-dependent protein catabolic process; regulation of proteasomal protein catabolic process; response to oxidative stress; apoptotic process; CD8-positive, alpha-beta T cell differentiation; CD8-positive, alpha-beta T cell homeostasis; cellular response to type I interferon; DNA damage response; DNA repair; flagellated sperm motility; immune system process; meiotic cell cycle; negative regulation of regulatory T cell differentiation; positive regulation of interleukin-2 production; positive regulation of tumor necrosis factor production; positive regulation of type II interferon production; proteasomal ubiquitin-independent protein catabolic process; regulation of G1/S transition of mitotic cell cycle; response to type II interferon; spermatogenesis; T-helper 1 cell differentiation; T-helper 17 cell differentiation; thymic T cell selection; protein catabolic process
Cellular component: cytoplasm; extracellular exosome; nucleus; proteasome complex; proteasome core complex; cytosol; nucleoplasm; proteasome core complex, beta-subunit complex; proteasome storage granule; spermatoproteasome complex; synaptic vesicle
Genetic constraint (gnomAD): Loss-of-function variants: 5 observed, 23.25 expected, observed/expected ratio (o/e) 0.22, 90% interval 0.11 to 0.45. The upper end of that interval is the gene's LOEUF score, 0.45, which puts it in group 2 of 6, group 1 being the genes least tolerant of losing a copy. Missense variants: 192 observed, 295.27 expected, observed/expected ratio (o/e) 0.65, 90% interval 0.58 to 0.73. Synonymous variants: 85 observed, 106.62 expected, observed/expected ratio (o/e) 0.8, 90% interval 0.67 to 0.95.
Homologues: Orthologues: chimpanzee PSMB3 (100% identical), dog PSMB3 (99% identical), macaque PSMB3 (99% identical), rabbit PSMB3 (99% identical), mouse Psmb3 (99% identical), rat Psmb3 (98% identical), pig PSMB3 (98% identical), guinea pig PSMB3 (97% identical), tropical clawed frog psmb3 (91% identical), zebrafish psmb3 (90% identical), Drosophila melanogaster Prosbeta3 (64% identical), Caenorhabditis elegans pbs-3 (51% identical). Paralogues in human: PSMB8 (24% identical), PSMB1 (24% identical), PSMB5 (23% identical), PSMB11 (22% identical), PSMB7 (22% identical), PSMB9 (22% identical), PSMA1 (21% identical), PSMB10 (20% identical), PSMB6 (20% identical), PSMA4 (20% identical), PSMA6 (20% identical), PSMA2 (19% identical), and 6 more.
Diseases named in the same sentence as PSMB3 in open-access papers:
PSMB3 is named in the same sentence as 23 diseases in open-access papers, as found by Europe PMC text mining. Sharing a sentence is not in itself a finding about the gene and the disease. The quoted sentences say what the papers report.
lung adenocarcinoma (4 papers, 2020 to 2022). A carcinoma that arises from the lung and is characterized by the presence of malignant glandular epithelial cells. "Moreover, the analysis of the Cancer Genome Atlas Lung Adenocarcinoma (TCGA-LUAD) dataset revealed that the high expression of PSMB3 is associated with worse survival in lung adenocarcinoma patients." (PMID 32545483, 2020). "Seven other 26S/20S proteasome subunits were isolated (q < 0.05; PSMD12, PSMB4, PSMA6, PSMB6, PSMC1, PSMD3, and PSMB3), illuminating the importance of the 26/20S proteasome integrity in lung adenocarcinoma genome maintenance." (PMID 34070461, 2021). "Moreover, a high PSMB3 expression corresponds to worse survival in patients with lung adenocarcinomas." (PMID 32545483, 2020).
COVID-19 (3 papers, 2021 to 2024). A disease caused by infection with severe acute respiratory syndrome coronavirus 2. "Fifteen proteasomal proteins showed an increase in serum levels of COVID-19 patients, most notably PSMA7, PSME1, PSMB3, PSMA4 and PSMA5, whereas PSMD2 was the only one with decreased levels." (PMID 37739942, 2023).
breast carcinoma (2 papers, 2010 to 2023). "This concurs with the observation that PSMB3 was co-expressed with ERBB2 in 34 breast cancer biopsies and also mapped within the same chromosomal location as the ERBB2 gene that is frequently amplified." (PMID 20543960, 2010).
multiple myeloma (2 papers, 2019 to 2020). "Although the PSMB3 subunit is not assumed to have direct proteolytic functions, silencing this subunit was found to contribute to bortezomib sensitivity in human multiple myeloma cells and in A549 NSCLC cells." (PMID 32545483, 2020).
Parkinson (2 papers, 2014 to 2024). "In addition, regarding neurodegenerative diseases (NDDs), several functions, including Huntington’s disease signaling (EGFR, MAPK1, PSMB3), neuroprotection by THOP1 in Alzheimer’s disease (AGT, MAPK1) and Parkinson’s signaling (MAPK1), were activated only in aged mice." (PMID 38590360, 2024).
gastric cancer (1 paper, 2015). A primary or metastatic malignant neoplasm involving the stomach. "TIIA treatment increased the likelihood of the occurrence of DNA damage in gastric cancer cells, which might stimulate cancer cells to increase PSMB3 expression." (PMID 25652794, 2015).
liver cancer (1 paper, 2024). An epithelial or non-epithelial malignant neoplasm that arises from the liver. "After analyzing six tumor-specific signatures (IDI1, GMPPA, NME1, PSMB3, SPTLC1 and EBP), the gene effect and gene dependency were measured in different non-cancerous cell lines and liver cancer lines of human HCC." (PMID 38927057, 2024).
ovarian carcinoma (1 paper, 2022). A malignant neoplasm originating from the surface ovarian epithelium. "Intriguingly, amplification of PSMB3, PSMB4, and PSMD4 have also been observed in breast- and ovarian cancer." (PMID 36123629, 2022).
cancer (11 papers, 2007 to 2024). A tumor composed of atypical neoplastic, often pleomorphic cells that invade other tissues. "This would be in line with our previous finding that the silencing of Sm genes induced a cancer-selective lethal splicing switch in the PSMB3 gene encoding one of the proteasome proteins." (PMID 39684842, 2024). "In the present study, no significant overexpression of PSMB3 mRNA was found in ccRCC tissues compared to normal tissues, but a positive correlation between the PSMB3 mRNA levels and patients' individual cancer stages and tumor grades was confirmed." (PMID 35693739, 2022). "On the other hand, Psmb3, Psmb6, and Psmb8 are the members of the proteasome subunit and have been found in most cancers." (PMID 33919822, 2021). "We next investigated if the AS switch in PSMB3 compromised cell viability and could thus explain the cancer cell-selective cytotoxicity of Sm gene silencing." (PMID 32545483, 2020). "It is unclear how up-regulation of PSMB3 expression contributes to cancer." (PMID 20543960, 2010). "Previous studies have shown that the expression of PSMB3 and RS2 is involved the development of cancer." (PMID 25652794, 2015). "Besides, mRNA levels of PSMB3 and PSMB6 in normal renal tissues were found to be higher than those in cancer tissues." (PMID 35693739, 2022). "Similarly, in 1M-84, DHFR* is integrated between PCGF2 (Mel-18) and PSMB3, approximately 1 Mb proximal to ERBB2, a gene frequently amplified in cancer." (PMID 17584934, 2007). "Furthermore, co-amplification of PSM genes located in close proximity to one another (e.g. PSMB5 and PSMB11, 14q11.2; PSMB4 and PSMD4, 1q21.3; PSMB8 and PSMB9, 6p21.32) or known cancer drivers (e.g. co-amplification of ERBB2 and PSMB3) were also frequently amplified together." (PMID 36123629, 2022).
tumor (4 papers, 2007 to 2025). "Finally, overexpression of the PSMB3 signature, was related to the metabolism of polyamines (but also to the more general proteasome function) and was found to differentially increase in tumor samples." (PMID 38927057, 2024). "We observed higher expression of PSMB1, PSMB3, and PSMB4 in tumour samples when compared to other subunits." (PMID 40862469, 2025). "Nevertheless, PCGF2 and PSMB3 are rarely amplified with ERBB2 in tumors, and PCGF2 has been reported to be a tumor suppressor." (PMID 17584934, 2007).
neurodegenerative disease (3 papers, 2024 to 2025). A disorder of the central nervous system characterized by gradual and progressive loss of neural tissue and neurologic function. "A high abundance of WNT, SEMG1, PSMB3, PSMC5, and other proteins in the advanced age group may be associated with risk for neurodegenerative diseases, malignancies, and impact sperm DNA integrity, spermatozoa survival and function, and fertilization." (PMID 40649876, 2025). "In the turquoise module, four hub lncRNAs (Gm5848, Zfp141, Rmrp, and Rb1) linked to hub mRNAs (Psmb3, Mad211, Sdhd, Ndufa6, Snrqd2, and Immp11) and are mainly related to NAFLD, multiple neurodegenerative diseases, oxidative phosphorylation, cell cycle, inflammation, and metabolic pathways." (PMID 40141450, 2025).
infection (2 papers, 2011 to 2017). The state of being infected such as from the introduction of a foreign agent such as serum, vaccine, antigenic substance or organism. "We have demonstrated that infection efficiency can be significantly affected by ablating proteins involved in sorting or degradation: calnexin, KDEL-R, β-COP, or PSMB3." (PMID 21625534, 2011).
PSMB3 also shares sentences with these, for which no sentence is quoted: Alzheimer disease (1 paper); breast disease (1); breast tumors (1); Cachexia (1); colorectal cancer (1); hereditary ataxia (1); Huntington disease (1); Insulin resistance (1); lung carcinoma (1); neurologic disorders (1); varicocele (1).